LCN2 (lipocalin 2)
Diseases named in the same sentence as LCN2 in open-access papers (continued):
Sharing a sentence is not in itself a finding about the gene and the disease.
COVID-19 (continued). "Furthermore, this work defines leukotriene B4 (LTB4) and lipocalin 2 (LCN2) as possible markers of COVID-19 and long-COVID and suggests novel opportunities for prevention and treatment." (PMID 36613462, 2022). "Similarly, we found that LCN2 was involved in functions of neutrophils in patients with COVID-19, including neutrophil degranulation, neutrophil activation involved in immune response, and NET formation." (PMID 35495713, 2022). "Compared with patients in general wards, patients with COVID-19 at ICU showed higher level of LCN2." (PMID 35495713, 2022). "Here, we found LCN2 was not only overexpressed in COVID-19 patients but also in infected cells." (PMID 33242255, 2020). "In addition, increased levels of serum lipocalin-2 during COVID-19 may scavenge iron and support the development of hypoferremia." (PMID 35849261, 2023). "Therefore, neutrophil-related LCN2 might serve as a potential biomarker for predicting disease severity in both patients with influenza and COVID-19." (PMID 35495713, 2022). "Interestingly, the listed genes reported as potent markers of critical illness in COVID-19 (CCL2, MMP8, IFI44, LCN2, SAA1) were identified by us as key regulators of both murine ALI and COVID-19-associated ARDS in human with the highest scores of degree centrality." (PMID 34807957, 2021). "Regarding the mediators related to neutrophilic activity, MMP8, lactoferrin, lipocalin-2, and MPO (all proteins potentially released by activated neutrophils) were augmented in the serum at all timepoints during COVID-19." (PMID 40710346, 2025). "We found that the amounts of Cp, Tf, HPX, LCN2, and SOD1 increased in PBMCs isolated from COVID-19 patients, compared to both the long-COVID group and the control group." (PMID 36613462, 2022). "Regarding the COVID-19 group, we observed an increasing trend in patients compared to the healthy controls that was found to be significant for Cp, Tf, HPX, and LCN2." (PMID 36613462, 2022). "The increase in the levels of histone H4, MPO, LCN2, PGLYRP1and DEFA3 detected in our proteomic analysis strongly support the observation that excessive NET formation occurs in severe COVID-19 patients." (PMID 36348270, 2022). "ELISA of an independent group of patients have confirmed that MPO, LCN2 and DEFA3 are increased in COVID-19 ICU/F patients when compared to HDand observed that LCN2 and DEFA3 can discriminate ICU/F from non-ICU COVID-19 patients." (PMID 36348270, 2022). "Markers like neutrophil-derived effectors (RETN), lipocalin-2 (LCN2), and matrix metallopeptidase 8 (MMP8) are among the best predictors of critical illness in COVID-19 provide perhaps the most concrete evidence to date that neutrophil activation is a hallmark of severe disease." (PMID 37144176, 2023). "As such, this is not a COVID-19-specific response, lipocalin-2 generally supports mucosal, cellular and systemic hypoferremia during inflammation." (PMID 35849261, 2023). "Among these alterations, we confirmed by ELISA that higher levels of the neutrophil granule proteins DEFA3 and LCN2 are present in COVID-19 patients requiring ICU admission when compared to non-ICU and healthy donors." (PMID 36348270, 2022). "In general, FCER1g, ICAM1, LAT, LCN2, and PLAU may be the main immune genes that are regulated by COVID-19 to induce olf and neurological dysfunction." (PMID 34504502, 2021). "Reported iron-related alterations in the sera of COVID-19 include decrements in iron, transferrin, transferrin saturation and hemoglobin (can show normal levels), and increments in ferritin, hepcidin (can be low), soluble transferrin receptor (in ICU patients) and lipocalin-2." (PMID 35849261, 2023). "Conversely, DEFA3 and LCN2/NGAL shows significant differences between COVID-19 ICU and non-ICU patients confirming that neutrophil activation could be a hallmark of COVID-19 severity." (PMID 36348270, 2022).
COVID-19 (continued). "That higher levels of LCN-2 are found at 9 weeks after severe COVID-19 illness compared with that in nonsevere cases suggests these patients may have ongoing neutrophil activation that could be amenable to targeted therapy." (PMID 34111030, 2021). "Therefore, examining the expression features of LCN2, STAT1 and UBE2L6 in different clinical contexts such as age, gender and smoking status could help us learn more about the pathogenesis of COVID-19 in different populations." (PMID 33242255, 2020).
type 2 diabetes (70 papers, 2007 to 2026). "Obese and type 2 diabetic patients have been characterized with increased levels of LCN2 in both circulation and adipose tissue and elevated serum lipocalin‐2 was independently associated with impaired glucose regulation and type 2 diabetes." (PMID 39511728, 2025). "Adding to experimental investigations, they described that the blood lipocalin 2 level was inversely associated with body weight and HbA1c in patients with type 2 diabetes." (PMID 35216490, 2022). "If FPG was replaced by 2hPG in both models, lipocalin-2 or RBP4 remained as a significant factor associated with subclinical atherosclerosis in type 2 diabetes (OR 2.28, 95% CI 1.08–4.83, P = 0.031; OR 1.15, 95% CI 1.09–1.21, P<0.001, respectively)." (PMID 23799122, 2013). "Serum lipocalin-2 was independently associated with subclinical atherosclerosis in type 2 diabetes (OR 2.10, 95% confidence interval (CI) 1.06–4.16, P = 0.033), together with age (P<0.001), BMI (P = 0.001) and FPG (P = 0.016)." (PMID 23799122, 2013). "Our findings suggest that elevated serum lipocalin-2 is closely and independently associated with impaired glucose regulation and type 2 diabetes." (PMID 22292925, 2012). "In this work, we focus on exploring the role of LCN2 in metabolic health and appetite regulation within the central nervous system of mice with type 2 diabetes." (PMID 39808380, 2025). "Lipocalin-2 (LCN2) is associated with various obesity-related disorders, such as Type 2 diabetes and non-alcoholic fatty liver disease." (PMID 39564133, 2024). "Circulating TonEBP and LCN2 levels were higher in experimental diabetic mice or type 2 diabetic patients with cognitive impairment." (PMID 34844610, 2021). "Serum LCN2 protein levels were significantly elevated in patients with type 2 diabetes or impaired glucose tolerance as well as in obese women." (PMID 34903175, 2021). "Animal models of type 2 diabetes and nonalcoholic steatohepatitis showed increased LCN2 secretion, which recruits inflammatory cells and induces proinflammatory cytokines, suggesting that LCN2 induces sterile inflammation." (PMID 34359830, 2021). "Therefore, this study aimed to investigate the association of LCN2 with DPN in type 2 diabetes (T2D)." (PMID 34636748, 2021). "In conclusion, our study suggests that serum lipocalin-2 or RBP4 levels reflect subclinical atherosclerosis in adults with newly diagnosed type 2 diabetes." (PMID 23799122, 2013). "In this study, we also observed serum Lipocalin-2 elevation in both type 2 diabetes and impaired glucose regulation." (PMID 22292925, 2012). "In conclusion, our study indicates that serum lipocalin-2 is independently correlated with impaired glucose regulation and type 2 diabetes." (PMID 22292925, 2012). "In this study, we found a strong correlation between serum lipocalin-2 levels and impaired glucose regulation as well as type 2 diabetes in a middle-aged and elderly Chinese population." (PMID 22292925, 2012). "Pap and Lcn2 were identified as the genes most strongly upregulated in islets from diabetic GK rats (a model for type 2 diabetes)." (PMID 17521427, 2007). "The role of LCN2 in the energy metabolism of type 2 diabetes is controversial and unclear." (PMID 39808380, 2025). "Previous studies have shown a positive association between circulating LCN2 and carotid intima-media thickness and subclinical atherosclerosis in type 2 diabetes, suggesting a potential role of LCN2 as a member of the lipoprotein family in atherosclerosis pathogenesis." (PMID 37543589, 2023). "However, we previously found that subjects with LADA had distinct cytokine profiles compared with subjects with type 2 diabetes and type 1 diabetes regarding lipocalin 2 (LCN2), adiponectin, IL-6, and high-sensitivity C-reactive protein (hs-CRP)." (PMID 36090989, 2022).
type 2 diabetes (continued). "Similarly, if lipocalin-2 was replaced by RBP4 in the model, RBP4 was independently associated with subclinical atherosclerosis in type 2 diabetes (OR 1.16, 95% CI 1.10–1.22, P<0.001)." (PMID 23799122, 2013). "We confirmed the strong and positive association between lipocalin-2 and CRP levels observed in previous studies, suggesting elevated serum lipocalin-2 in prediabetes and type 2 diabetes might associate with chronic inflammation." (PMID 22292925, 2012). "Lipocalin-2, an inflammatory marker found in various tissues, including adipose tissue, has been associated with atherosclerosis development and CAD severity, and its levels increase in response to factors such as body mass, type 2 diabetes mellitus (T2DM), and insulin resistance." (PMID 38068263, 2023). "Serum lipocalin-2 was significantly higher in subjects with isolated impaired fasting glucose, isolated impaired glucose tolerance, combined impaired fasting glucose/impaired glucose tolerance and newly-diagnosed type 2 diabetes than in those with normal glucose regulation." (PMID 22292925, 2012). "In this study, we assessed serum lipocalin-2 and RBP4 concentrations in patients with newly diagnosed type 2 diabetes in relation to subclinical atherosclerosis, as measured by carotid, femoral and iliac arteries." (PMID 23799122, 2013). "Taken together, it is possible that lipocalin-2 and RBP4 mediate atherogenesis via enhancing vascular inflammation in type 2 diabetes." (PMID 23799122, 2013). "Serum levels of lipocalin-2 and RBP4 were measured in 284 type 2 diabetic patients." (PMID 23799122, 2013). "In addition, urinary NGAL (LCN2) levels were higher in patients with type 2 diabetes than in those without diabetes and higher in patients with urinary albumin than in those without urinary albumin." (PMID 36353239, 2022). "LCN2 has an osteokine important for appetite regulation; in type 2 diabetes (T2D) it is not known whether appetite regulation mediated by LCN2 in the brain is altered." (PMID 39808380, 2025).
renal dysfunction (64 papers, 2009 to 2026). "Both the serum and plasma levels of LCN2 variants, as well as their ratios are associated with increased cardiometabolic risk, whereas those in urine are correlated with renal dysfunction." (PMID 34938273, 2021). "Lipocalin-2 (LCN2), also known as neutrophil gelatinase-associated lipocalin (NGAL), has been proposed as a biomarker for renal dysfunction, MetS, and T2DM." (PMID 40137149, 2025). "In individuals with renal dysfunction and DLP, the level of lipocalin-2 was 1.4 times lower, and amylin was 1.1 times higher than in individuals without DLP." (PMID 37623488, 2023).
metabolic syndrome (59 papers, 2012 to 2026). A cluster of metabolic risk factors for CARDIOVASCULAR DISEASES and TYPE 2 DIABETES MELLITUS. "Further investigation is still needed to explore the direct effect of circulating LCN2 on the cognitive function of patients with metabolic syndrome as well as the mechanisms underlying these changes." (PMID 35302058, 2022). "It has been shown that AGHD, similar to metabolic syndrome, is strongly associated with a chronic inflammatory state and that serum levels of lipocalin-2 (LCN2) are significantly elevated in patients with AGHD compared to the healthy population." (PMID 34220710, 2021). "The ubiquitous presence of LCN-2 in different cellular districts of the human body makes it an interesting candidate as a marker of various pathological conditions, not only for metabolic syndrome." (PMID 38396890, 2024). "Lipocalin 2 (LCN2) is a glycoprotein present as a cytokine in the adipose tissue of obese individuals with metabolic syndrome when there is low-level systemic inflammation." (PMID 36362238, 2022). "It has been reported that the blood levels of lipocalin-2 are higher in people with metabolic syndrome; however, there were only 18 patients with metabolic syndrome in the study." (PMID 36579566, 2022). "To summarize, the current evidence shows that LCN2 is involved in insulin sensitivity, glucose metabolism, vascular homeostasis, and hyperglycemia related to metabolic syndromes." (PMID 33945675, 2021). "RBP4 and FABP4 are positively associated with metabolic syndrome, while APOD and LCN2 are ubiquitously expressed proteins with deleterious or beneficial effects, depending on their anatomical site of expression." (PMID 34638803, 2021). "Lipocalin 2 (LCN2), also associated with neutrophil gelatinase-associated lipocalin (NGAL), is a glycoprotein identified as the cytokine of adipose tissue present in low-level systemic inflammation in obese patients with metabolic syndrome." (PMID 33807959, 2021). "In a study done at the Shanghai diabetic institute, LCN2 was significantly correlated to metabolic syndrome indicated by waist circumference." (PMID 28709459, 2017). "Finally, LCN2 can control metabolic homeostasis, including insulin sensitivity, hyperglycemia, and dyslipidemia through the modulation of NF‐κB, C/EBP signaling, HbA1c level, and body fat mass." (PMID 33945675, 2021). "LCN2 also acts as an adipokine in adipose tissue, and increased blood levels of LNC2 are associated with metabolic syndrome, and may be a mediator contributing to the low levels of systemic inflammation observed in these patients." (PMID 34639156, 2021). "Lcn2 is considered to be the marker of many inflammatory diseases and involved in various inflammations, including intestinal inflammation, skin inflammation, and metabolic syndrome." (PMID 31781104, 2019). "In male mice, a lack of LCN2 has an impact on energy metabolism, causing increased adiposity, adipocyte hypertrophy, dyslipidemia, and fatty liver." (PMID 29234288, 2017). "In the liver, LCN2 modulates HDL flux through the Nedd4-1-SR-BI axis, with experimental models showing that hepatocyte-derived LCN2 can reduce atherosclerosis, underscoring its direct influence on HDL metabolism and dyslipidemia." (PMID 41303567, 2025). "However, whether LCN2 has a detrimental or beneficial role in metabolic syndrome is still unclear." (PMID 35302058, 2022). "The association between Lipocalin-2 (LCN2) and cognition in patients with metabolic syndrome (MetS) has not been thoroughly investigated." (PMID 35302058, 2022). "LCN2 enhances macrophage scavenger receptor expression, promotes foam cell formation, and shows elevated circulating levels in individuals with greater CAD burden, linking it to dyslipidemia-driven atherogenesis." (PMID 41303567, 2025). "Although LCN2 was postulated as a metabolic syndrome-related protein, we did not observe any correlation between this protein and BMI in RA patients." (PMID 39403549, 2024).
metabolic syndrome (continued). "Furthermore, in addition to finding the links between the adipokine levels and infections, this study also revealed increasing levels of LCN-2 in patients presenting with T2DM and dyslipidemia." (PMID 32983730, 2020).
injury (58 papers, 2012 to 2026). Damage inflicted on the body as the direct or indirect result of an external force, with or without disruption of structural continuity. "Neutrophil gelatinase-associated lipocalin (Ngal, Lcn2), a small protein of the lipocalin family, was generally considered as a biomarker of acute renal injury." (PMID 35308536, 2022). "In the bleomycin-induced lung injury mouse model, a higher dose of bleomycin resulted in higher LCN2 levels and shorter survival." (PMID 38704585, 2024). "Lipocalin-2 (LCN2), a member of the lipocalin family, functions as an acute-phase protein following brain injury." (PMID 37353794, 2023). "Although previous studies have shown that NF-κB is involved in the neuroinflammatory response induced by brain injury, the role and mechanism of NF-κB-mediated transcriptional activation of LCN2 in neonatal HIBD is unclear." (PMID 36671050, 2023). "Brain injury or infection can result in neuroinflammation that may encourage the release of lipocalin 2 (LCN2) from astrocytes." (PMID 38751782, 2024). "This study aimed to determine whether circulatory LCN2 could be a systemic biomarker in patients with IPF and to investigate the role of LCN2 in a bleomycin-induced lung injury mouse model." (PMID 38704585, 2024). "In LPS-treated mice, lipocalin-2 knockout significantly decreased iron-stained macrophages and oxidative stress, suggesting that lipocalin-2 is a potential therapeutic target for LPS-induced acute lung injury." (PMID 37629516, 2023). "Furthermore, deferiprone inhibited inflammation, oxidative stress, and phagocytosis in RAW264.7 cells with high LCN2 levels, as well as LPS-induced acute lung injury in WT and LCN2 KO mice." (PMID 36923935, 2023). "In the central nervous system, it has been shown that lipocalin-2 is a modulator of deramification and apoptosis of activated microglial cells, reactive astrocytosis in response to brain injury and increased plasma Lcn-2 levels have been shown to positively correlate with mild cognitive impairment." (PMID 23593384, 2013). "Moreover, LCN2 expression levels may reflect the severity of lung injury, and LCN2 may be a protective factor against bleomycin-induced acute lung injury and oxidative stress." (PMID 38704585, 2024). "In models of acute liver injury, it attenuates ferroptosis via activation of the AMPK/sequestosome 1/NRF2 pathway, while in cardiomyocytes, ferroptosis is suppressed through downregulation of lipocalin 2 (LCN2)." (PMID 41311485, 2025). "As brain injury-induced increases in LCN2 expression are unlikely to reach such high concentrations, these data exclude an effect of LCN2 on OPC proliferation." (PMID 35817941, 2022). "Since LCN2 has been discussed as a blood-based marker for kidney injury, we retrospectively reviewed medical files of all AD and VBI cases to identify those with kidney injury and included this condition in the regression model as an additional covariate." (PMID 32001681, 2020). "Additionally, higher LCN2 expression levels may reflect the severity of lung injury, and LCN2 may be protective against BLM-induced acute lung injury and oxidative stress." (PMID 38704585, 2024). "Moreover, lipocalin 2 (Lcn2) (the mouse homolog of human NGAL) expression has been found to be markedly increased in septic mice with acute lung injury compared to those without acute lung injury." (PMID 36221054, 2022).